IARS1 (isoleucyl-tRNA synthetase 1)
Description:
Catalyzes the specific attachment of an amino acid to its cognate tRNA in a 2 step reaction: the amino acid (AA) is first activated by ATP to form AA-AMP and then transferred to the acceptor end of the tRNA.
Synonyms: IRS; IleRS; IARS; ILRS; GRIDHH; PRO0785
Tractability: Small molecule: it belongs to a druggable protein family. PROTAC: ubiquitination databases record sites on it; a small molecule that binds it is known.
Target class: Enzyme; Ligase
Gene: Protein-coding gene on chromosome 9 (92,210,207 to 92,293,854, reverse strand). Ensembl gene ENSG00000196305.
Subcellular location: Cytoplasm; Cytoplasm, cytosol
Subcellular location (Human Protein Atlas): Cytosol; Nucleoplasm
Pathways (Reactome):
Developmental Biology: Transcriptional and post-translational regulation of MITF-M expression and activity
Metabolism: Selenoamino acid metabolism
Metabolism of proteins: Cytosolic tRNA aminoacylation
Gene Ontology:
Molecular function: GTPase binding; isoleucine-tRNA ligase activity; protein binding; aminoacyl-tRNA deacylase activity; aminoacyl-tRNA ligase activity; ATP binding; nucleotide binding; tRNA binding
Biological process: isoleucyl-tRNA aminoacylation; osteoblast differentiation; tRNA aminoacylation for protein translation; aminoacyl-tRNA metabolism involved in translational fidelity
Cellular component: aminoacyl-tRNA synthetase multienzyme complex; cytoplasm; cytosol; extracellular exosome; membrane
Genetic constraint (gnomAD): Loss-of-function variants: 69 observed, 92.54 expected, observed/expected ratio (o/e) 0.75, 90% interval 0.61 to 0.91. The upper end of that interval is the gene's LOEUF score, 0.91, which puts it in group 3 of 6, group 1 being the genes least tolerant of losing a copy. Missense variants: 986 observed, 1,076.3 expected, observed/expected ratio (o/e) 0.92, 90% interval 0.87 to 0.97. Synonymous variants: 373 observed, 392.55 expected, observed/expected ratio (o/e) 0.95, 90% interval 0.87 to 1.03.
Homologues: Orthologues: rabbit IARS1 (93% identical), macaque IARS1 (92% identical), pig IARS1 (92% identical), chimpanzee IARS1 (91% identical), rat Iars1 (91% identical), mouse Iars1 (91% identical), dog IARS1 (90% identical), guinea pig IARS1 (89% identical), tropical clawed frog iars1 (78% identical), zebrafish iars1 (74% identical), Drosophila melanogaster IleRS (53% identical), Caenorhabditis elegans iars-1 (51% identical). Paralogues in human: IARS2 (20% identical), VARS2 (18% identical), VARS1 (17% identical), LARS1 (15% identical), LARS2 (12% identical), MARS1 (10% identical), MARS2 (7% identical).
Diseases named in the same sentence as IARS1 in open-access papers:
IARS1 is named in the same sentence as 51 diseases in open-access papers, as found by Europe PMC text mining. Sharing a sentence is not in itself a finding about the gene and the disease. The quoted sentences say what the papers report.
hepatopathy (4 papers, 2019 to 2025). "Growth retardation, impaired intellectual development, hypotonia, and hepatopathy (GRIDHH) is a rare disease caused by compound heterozygous variations in the isoleucyl-tRNA synthetase 1 (IARS1) gene." (PMID 40635052, 2025). "Cytosolic isoleucyl-tRNA synthetase (IARS1) deficiency, an exceptionally rare autosomal recessive inherited disorder, is characterized by multiple system involvement, including growth retardation, intellectual developmental disorder, hypotonia, and hepatopathy." (PMID 39950113, 2025). "In contrast, defects in cytoplasmic IARS1, encoded by IARS1 (MIM# 600709), cause autosomal recessive growth retardation, impaired intellectual development, hypotonia, and hepatopathy (GRIDHH, OMIM# 617093)." (PMID 40365325, 2025). "Variants in the IARS1 gene have been linked to a spectrum of clinical manifestations, including growth retardation, impaired intellectual development, hypotonia, and hepatopathy (GRIDHH; OMIM #617093)." (PMID 40635052, 2025). "Pathogenic variants in IARS1 (MIM# 600709), encoding cytoplasmic isoleucyl‐tRNA synthetase, have been associated with autosomal recessive growth retardation, impaired intellectual development, hypotonia, and hepatopathy (GRIDHH, OMIM# 617093)." (PMID 40365325, 2025).
Failure to thrive (2 papers, 2022 to 2025). Failure to thrive (FTT) refers to a child whose physical growth is substantially below the norm. "In these disease models, we confirmed that biallelic, but not monoallelic, IARS1I1174N mutations impaired organoid expandability, reflecting the failure to thrive observed in patients with biallelic IARS1 mutations." (PMID 35232966, 2022).
liver failure (2 papers, 2022 to 2025). A liver disease characterized by the liver losing or has lost all of its function. "The liver, as a highly metabolically active organ, is significantly affected by IARS1 deficiency, exhibiting a wide range of phenotypes, including recurrent liver failure." (PMID 40635052, 2025). "It is nevertheless recommended to exercise caution when contemplating protein intake in patients with IARS1 deficiency and liver failure." (PMID 40635052, 2025).
pulmonary alveolar proteinosis (2 papers, 2025). A rare lung disorder characterized by the filling of the pulmonary alveoli with proteinaceous material which stains positive with periodic acid-Schiff stain. "In this study, we reported a case of IARS1 deficiency in a 5-month-old Chinese boy who presented with a rare phenotype of pulmonary alveolar proteinosis (PAP) as the initial and predominant manifestation." (PMID 39950113, 2025). "Pulmonary alveolar proteinosis (PAP) is a rare phenotype of IARS1 deficiency, having been reported in only two siblings from the same family." (PMID 39950113, 2025).
acute liver failure (1 paper, 2025). Rapid deterioration of liver function causing encephalopathy and coagulopathy. "This suggests that IARS1 deficiency may be a potential cause of acute liver failure in infants and children, with likely fatal consequences." (PMID 40635052, 2025).
anemia (1 paper, 2025). A reduction in the number of red blood cells, the amount of hemoglobin, and/or the volume of packed red blood cells. "The patient was diagnosed with IARS1 deficiency, cholestasis, anemia, hypoalbuminemia, coagulation abnormality and hypoglycemia." (PMID 40635052, 2025).
cholestasis (1 paper, 2025). Impairment of the bile flow caused by obstruction within the liver, or outside the liver in the bile duct system. "Three children were admitted for further investigation, due to a suspicion of cholestasis and/or cough caused by IARS1 deficiency." (PMID 40635052, 2025).
fatty liver (1 paper, 2023). "In conclusion, the hypomorphic mutation of IARS1 in mice, established in this study, replicates the pathophysiology of IARS1 disorder, including growth retardation and hepatic steatosis, observed in preweaning humans and cattle." (PMID 37108118, 2023).
Immunodeficiency (1 paper, 2025). Failure of the immune system to protect the body adequately from infection, due to the absence or insufficiency of some component process or substance. "With these findings, it is likely that IARS1 deficiency not only leads to immunodeficiency but also to autoinflammatory phenotypes." (PMID 40365325, 2025).
stomach cancer (1 paper, 2024). "The expression of EIF4E, EXOSC1, IARS1, IGFBP1, and SPCS1 was found to be upregulated in stomach cancer cell lines, while TSPYL2 and TUBB2A showed downregulated expression." (PMID 38700505, 2024).
tumor (17 papers, 2013 to 2023). "In conclusion, this study identifies an anti-tumor axis of excess isoleucine-IARS1-PTEN, which provides a new theoretical basis for amino acid supplementation in treating tumors." (PMID 36820928, 2023). "However, in excess isoleucine, the interaction between IARS1 and PTEN is enhanced and promotes its accumulation to the nucleus, thereby exerting PTEN transcriptional regulation of anti-tumor effects." (PMID 36820928, 2023).
cancer (13 papers, 2012 to 2025). A tumor composed of atypical neoplastic, often pleomorphic cells that invade other tissues. "The disruption of ARSs, including DARS1, IARS1, and KARS1, has been associated with cancer progression." (PMID 40867231, 2025). "Furthermore, because IARS1-deficient cells become more sensitive to PARP inhibitors, IARS1 is being considered a potential target for cancer therapy." (PMID 39062673, 2024). "Although BRCA1 mutations are associated with multiple types of cancer, there are no reports on the involvement of IARS1 mutations in carcinogenesis." (PMID 39062673, 2024). "There are a few aaRSs that are downregulated in multiple cancer types, including HARS2 (n = 6), WARS1 (n = 4), CARS2 (n = 4), IARS1 (n = 3), RARS2 (n = 3), VARS2 (n = 3), and AIMP3/EEF1E1 (n = 3), suggesting these aaRSs may possess certain specific cancer-inhibiting roles." (PMID 33266490, 2020).
mitochondrial disease (3 papers, 2023 to 2024). "Mutations in IARS1 cause weak calf syndrome in cattle and mitochondrial diseases in humans, leading to growth retardation and liver dysfunction." (PMID 39062673, 2024). "Recent human genomic studies about pediatric mitochondrial diseases also identified mutations in the IARS1 gene." (PMID 37108118, 2023). "Notably, recent genomic analyses of mitochondrial diseases in children also identified similar mutations in the IARS1 gene." (PMID 37108118, 2023). "In recent years, mutations in both alleles of IARS1 and IARS2 have been linked to mitochondrial diseases." (PMID 39062673, 2024). "This review aims to explore the relationship between IARS1 and IARS2 and these diseases, providing a comprehensive overview of their association with mitochondrial diseases." (PMID 39062673, 2024). "Mutations in IARS1 and IARS2 have recently been linked to mitochondrial diseases." (PMID 39062673, 2024).
autosomal recessive inherited disorder (1 paper, 2025). "IARS1 deficiency, an extremely rare autosomal recessive inherited disorder, is characterized by multiple system involvement, including growth retardation, intellectual disability, muscular hypotonia, and infantile hepatopathy (GRIDHH, OMIM 617093)." (PMID 39950113, 2025).
neurological disorders (1 paper, 2025). "Much like other deficiencies associated with ARSs, IARS1 deficiency has been linked to a range of neurological disorders, with notable phenotypic variation observed." (PMID 40635052, 2025).
IARS1 also shares sentences with these, for which no sentence is quoted: pancreatic cancer (5 papers); Insulin resistance (3); Intellectual disability (3); liver disease (3); Autoimmunity (2); diabetes (2); hepatocellular carcinoma (2); infection (2); melanoma (2); metabolic disease (2); oral cavity squamous cell carcinoma (2); prostate carcinoma (2); Zinc deficiency (2); autoimmune disorders (1); breast carcinoma (1); cervical cancer (1); cholangiocarcinoma (1); chronic hepatitis B (1); colon cancer (1); deafness (1); development (1); Esophageal Carcinoma (1); growth retardation (1); heart failure (1); Hyperglycemia (1); Hypoalbuminemia (1); Hypoglycemia (1); inflammatory bowel disease (1); metastatic tumor (1); microcephaly (1).
A further 6 diseases each share a sentence with IARS1 in 1 paper.